TSPAN7 (tetraspanin 7)
Diseases named in the same sentence as TSPAN7 in open-access papers (continued):
Sharing a sentence is not in itself a finding about the gene and the disease.
tumor (continued). "In TCGA, CGGA_325 and CGGA_693 datasets, we found that with the increase of tumor grade, TSPAN7 expression decreased gradually." (PMID 36845098, 2023). "CD74 and TSPAN7 expression was negatively correlated with tumor purity while positively correlated with the level of multiple immune cells." (PMID 36911401, 2023). "Previous reports have pointed out that direct correlations were noted between TSPAN7 upregulation and advanced tumor stage, lymph node status, and adenocarcinoma." (PMID 37516981, 2023). "Further receiver operating characteristics (ROC) curve analyses from the GSE33383 and GSE42352 datasets revealed Tspan7 to be a valuable biomarker capable of differentiating between healthy and OS tumor tissues and cell lines." (PMID 35524311, 2022). "These B cells predominately produced IgA that specifically recognized these targets expressed in HGSOC tumour cells, as well as recombinant TSPAN7 and BDNF." (PMID 33536615, 2021). "The results showed that overexpression of TSPAN7 had a significant effect on tumor growth inhibition, while knockdown of TSPAN7 promoted tumor growth." (PMID 32694936, 2020). "In conclusion, we have shown, for the first time, the tumor-inhibiting effects of TSPAN7 on human BCa." (PMID 33489923, 2020). "Among these DE-MTGs, upregulated RACGAP1, RARRES3, TPX2, MMP28, GPR87, and KIF14 with HR > 1 were regarded as oncogenes, whereas downregulated TSPAN7 with HR < 1 was regarded as a tumor suppressor." (PMID 33033514, 2020). "Consistent with the TCGA database analysis, the downregulation of TSPAN7 expression at both the transcriptional and translational levels in tumor specimens predicted high malignancy and a poor prognosis in BCa patients." (PMID 33489923, 2020). "Consistent with the results of integrated analysis, mRNA expression of RACGAP1, RARRES3, TPX2, MMP28, GPR87, and KIF14 was significantly upregulated in PDAC tumor tissues, whereas TSPAN7 was significantly downregulated." (PMID 33033514, 2020). "Analyses of clinicopathological features showed that TSPAN7 was an independent prognostic factor of BCa that was significantly correlated with T stage and tumor grade, and low expression of TSPAN7 predicted a poor prognosis (OS) in BCa patients." (PMID 33489923, 2020). "By regulating the exchange of substances, TSPAN7 influences the activity of tumor cells directly." (PMID 41031049, 2025). "Because of heterogeneity in tumor microenvironment, we further investigated whether TSPAN7 was specifically expressed in glial lineage." (PMID 36845098, 2023). "Tetraspanin7 (Tspan7) is a member of this superfamily that plays documented roles in hippocampal neurogenesis, synaptic transmission, and malignant transformation in certain tumor types." (PMID 35524311, 2022). "In the present study, we found that abrogation of Tspan7 resulted in the impaired proliferation of OS tumor cells relative to control cells, suggesting that Tspan7 may function as a key regulator of OS development and/or progression." (PMID 35524311, 2022). "Currently, it remains poorly understood whether Tspan7 is able to interact with specific integrin partners to regulate tumor progression." (PMID 35524311, 2022). "Consequently, we explored the expression of Tspan7 in OS cell lines and tumor tissue samples and found it to be elevated therein relative to corresponding controls." (PMID 35524311, 2022). "In further support of antibody-dependent cellular phagocytosis, splenic myeloid cells from tumour-bearing (CD89-deficient) mice bound IgA through Fcα/μR (CD351), and killed OVCAR3 targets more effectively upon coating with TSPAN7-reactive IgA." (PMID 33536615, 2021). "Importantly, there were increases in CD351+ myeloid cells at tumour beds after treatment with TSPAN7 antibodies as compared to control IgA." (PMID 33536615, 2021). "Nude tumor formation test used to verify the tumor suppressive effect of TSPAN7 in vivo." (PMID 32694936, 2020).
tumor (continued). "TSPAN7 could be an oncogene that promotes apoptosis and inhibits tumor growth and cell cycle progression in BCa via the regulation of multiple key components of the PTEN/PI3K/AKT pathway." (PMID 33489923, 2020). "In vivo, tumor growth in nude mice bearing tumor xenografts could be obviously affected by overexpression of TSPAN7." (PMID 33489923, 2020). "Furthermore, high expression of TSPAN7 was negatively correlated with a high T stage and tumor grade in BCa." (PMID 33489923, 2020). "Animal experiments have also confirmed that TSPAN7 has a tumor suppressive effect in vivo." (PMID 32694936, 2020). "Finally, we established a xenograft tumor model using nude mice and demonstrated that TSPAN7 inhibited tumorigenesis in vivo." (PMID 33489923, 2020). "Interestingly, TSPAN7 is a double‐edged sword in tumor cells." (PMID 41031049, 2025). "Interestingly, with the expression levels of TSPAN7 gradually decreasing, the tumor became more malignant and the corresponding biological behaviors, such as cell proliferation capacity, EMT, angiogenesis, DNA repair, as well as MAPK pathways, were more active." (PMID 36845098, 2023). "Therefore, we hypothesized that TSPAN7 may affect the binding of PDL1 to PD1 in tumor cells by changing the morphology of tumor cells, and then affect the efficacy of anti-PDL1 immunotherapy." (PMID 36845098, 2023). "Recombinant TSPAN7 and BDNF IgA antibodies are confirmed to bind tumor cells and recombinant proteins, and control mouse tumor growth." (PMID 40356924, 2025). "This study demonstrates that TSPAN7 is downregulated in CRC and inhibits tumor cell proliferation and invasion." (PMID 41031049, 2025). "Conversely, Tspan7, CD82, CD63, Tspan7, and Tspan9 are downregulated, suppressing digestive system tumor cell metastasis." (PMID 38389703, 2024). "Moreover, by analyzing the relationship between TSPAN7 expression and immune cell infiltration in multiple datasets, we found that TSPAN7 was significantly negatively correlated with the immune infiltration of tumor-related macrophages, especially M2-type macrophages." (PMID 36845098, 2023). "Patients with high TSPAN7 expression had significantly longer disease free survival (DFS) and tumor specific survival (TSS)." (PMID 36776322, 2023). "Some tetraspanins, such as TSPAN15, can enhance tumor cell proliferation ability, while other family members, such as CD9, CD63, TSPAN1, TSPAN7, and TSPAN31, can antagonize apoptosis and facilitate tumor cell survival." (PMID 34540692, 2021). "Conversely, the TSPAN7 IgA antibody mediated tumor control requires the Fc region and is independent of NK cells, and promotes ADCP in vitro." (PMID 40356924, 2025). "To explore whether TSPAN7 can influence tumor cell proliferation through STK11, we treated TSPAN7‐overexpressing CRC cells with radicicol, a known STK11 inhibitor." (PMID 41031049, 2025). "For example, a study concerning multiple myeloma found that overexpression of tetraspanin 7 reduced tumor size in mouse model but did not affect cell proliferation in an in vitro model." (PMID 39031113, 2024). "Moreover, low expression of TSPAN7 was highly expressed in IDH wildtype, MGMT unmethylated and MES-like tumor." (PMID 36845098, 2023). "To evaluate whether TSPAN7 exerts antitumor effects in vivo, we established a nude mouse model with HCC-LM3 tumor xenografts." (PMID 32694936, 2020). "The possible explanation is that, with the gradually decrease of TSPAN7 expression, tumor cells will promote the recruitment of macrophages and mediate the polarization of M1 macrophages to M2 macrophages, and thus remodeling TIME and inhibiting anti-tumor immune response." (PMID 36845098, 2023).
cancer (14 papers, 2015 to 2024). A tumor composed of atypical neoplastic, often pleomorphic cells that invade other tissues. "TSPAN7 plays a role in cell and membrane compartmentalization and regulates the trafficking and function of its partner proteins, associated with cancer metastasis-suppressive interactions." (PMID 34276651, 2021). "As a result, much effort has been expended in trying to explore differential expression of CD74 or TSPAN7 in cancer cell strains, ignoring the influence of immune infiltration." (PMID 36911401, 2023). "Tspan7 has previously been shown to play either pro- or anti-oncogenic roles in different cancer types." (PMID 35524311, 2022). "Unpaired samples in pan-cancer demonstrated there were significant differences in TSPAN7 expression in 17 cell lines in TCGA." (PMID 36685274, 2022). "Paired samples in pan-cancer demonstrated there were significant differences in TSPAN7 expression in 13 cell lines in TCGA." (PMID 36685274, 2022). "Further research will be necessary to explore whether Tspan7 plays conflicting roles in cancer regulation due to its different chaperones or downstream signaling pathways." (PMID 38389703, 2024). "Meanwhile, the function of TSPAN7 in cancer invasion and metastasis is context-dependent." (PMID 36941633, 2023). "Evidence has shown the context-dependent role of TSPAN7 in cancer." (PMID 36941633, 2023). "Knocking down Tspan7 was sufficient to suppress the proliferation of OS cancer cells." (PMID 35524311, 2022). "Upon GO and KEGG analyses, Tspan7 was also likely to be involved in OS cancer cell metastasis." (PMID 35524311, 2022). "The result showed that the TSPAN7 expression in LGG and GBM was significantly higher than that in other system cancers, and the expression level in LGG was significantly higher than that in GBM." (PMID 36845098, 2023). "Under the differentially expressed genes we identified several genes previously related to cancer including the up-regulated SSX1, SSX2, RXFP2, RYR2 and the down-regulated CSTA, TSPAN7, NEO1, S100A, SERPINB5 and SEPP1." (PMID 25857299, 2015).
infection (4 papers, 2020 to 2025). The state of being infected such as from the introduction of a foreign agent such as serum, vaccine, antigenic substance or organism. "Expression of dynamin 2 (DNM2) and tetraspanin 7 (TSPAN7) in DCs favors maintaining viral particles on the surface of DCs, whereas DCs deficient in DNM2 and TSPAN7 redistributed viral particles in micropinosomes, exhibiting reduced trans-infection ability." (PMID 35802715, 2022). "Additionally, genes related to cell adhesion such as ADGRF5, CAVIN2, FAT3, FILIP1, GSN, and TSPAN11 were downregulated in both the variants at 24hpi whereas CAV1, CAVIN1, GPC3, POSTN, SUSD2, and TSPAN7 were downregulated only after Delta variant infection at 24 hpi." (PMID 41200555, 2025). "We sought to investigate the crosstalk between DC maturation status, TSPAN7 expression and trans-infection." (PMID 32181159, 2020). "TSPAN7 has limited, if any effect on a second phase (from 20 to 40 h of co-culture) of T cells infection, which relies on HIV-1 replication." (PMID 32181159, 2020). "A TSPAN7 and actin nucleation-independent mechanism of trans-infection, relying on HIV-1 replication, was then at play." (PMID 32181159, 2020). "We have observed that TSPAN7 and actin nucleation were also involved in DC-mediated trans-infection of CD4+ T lymphocytes using transmitted/founder strains of HIV-1 (data not shown), which are CCR5-tropic and infect DCs more efficiently." (PMID 32181159, 2020). "The study then proceeds to concentrate on TSPAN7 and DNM2 and their role in trans-infection at the cell surface, whereas we focused on the trafficking of internalized virus." (PMID 32075937, 2020). "A second phase of HIV-1 transfer, observed during the next 20 h of co-culture experiments and accounting for less than a quarter of total T cells infection, is happening in an HIV replication-dependent manner and seems to rely less on TSPAN7 and actin nucleation." (PMID 32181159, 2020). "As the role of TSPAN7 in HIV-1 transfer was reported to be through actin-rich dendrites formation (Ménager and Littman, 2016), we next sought to monitor MDDCs morphology and dendrite formation at 4, 20, and 40 h following initiation of HIV-1 trans-infection experiments." (PMID 32181159, 2020).
psychiatric disorder (3 papers, 2020 to 2023). A disorder characterized by behavioral and/or psychological abnormalities, often accompanied by physical symptoms. "TSPAN7 was associated with the development of a variety of diseases, including psychiatric disorders and type 1 diabetes in pathological conditions." (PMID 36625203, 2023). "TSPAN7 knockout causes ASD-like phenotypes in rats through the integrin β1/FAK/SRC signal pathway, which provides novel insights into the role of TSPAN7 in psychiatric diseases, highlighting SRC as a potential target." (PMID 36625203, 2023). "Lee SA disclosed a previously uncharacterized role for TSPAN7 in the regulation of the expression and functional activity of the dopamine D2 (DRD2) receptor, which was implicated in multiple neurologic and psychiatric disorders by postendocytic trafficking." (PMID 33489923, 2020).
gastrointestinal tumors (2 papers, 2020 to 2025). "The current study postulated that TSPAN7 is downregulated in CRC, and it is possible that similar mechanisms may exist in other gastrointestinal tumors, although further validation is required." (PMID 41031049, 2025). "However, the role of TSPAN7 in tumors of the digestive system has not been confirmed." (PMID 32694936, 2020).
brain disease (1 paper, 2023). "Tspan7 was also found to be down-regulated in patients’ brains in a variety of diseases including ASD, HD, PD, and AD (*P < 0.05, **P < 0.01, n.s), implying the important role in brain disease." (PMID 36625203, 2023).
digestive system cancer (1 paper, 2020). A primary or metastatic malignant neoplasm involving any part of the digestive system. "Using qRT-PCR and Western blotting, we evaluated the expression of TSPAN7 in digestive system cancers." (PMID 32694936, 2020). "Bioinformatics analysis found that TSPAN7 is the only four-transmembrane protein with reduced expression in three types of digestive system cancers." (PMID 32694936, 2020).
infectious disease (1 paper, 2021). A disorder directly resulting from the presence and activity of a microbial, viral, or parasitic agent in humans. "In particular, CD9, CD63, CD81, CD82, CD151, and TSPAN7 (CD231) were implicated in numerous chronic and infectious disease pathologies." (PMID 34769038, 2021).
kidney diseases (1 paper, 2021). "It has been hard to find a direct link between FTCD or TSPAN7 and kidney diseases so far." (PMID 34276651, 2021).
metabolic disease (1 paper, 2025). A congenital disorder (due to inherited enzyme abnormality) or acquired (due to failure of a metabolically important organ) disorder resulting from an abnormal metabolic process. "Altogether, this study reveals that adipose tissue-specific modulation of TSPAN7 influences systemic metabolic homeostasis and presents a potential therapeutic strategy for metabolic diseases by targeting adipose tissue function." (PMID 40368161, 2025).
TSPAN7 also shares sentences with these, for which no sentence is quoted: acute myeloid leukemia (2 papers); adenocarcinoma (2); chronic lymphocytic leukemia (2); Huntington disease (2); schizophrenia (2); chronic myeloid leukemia (1); colon cancer (1); dementia with Lewy bodies (1); epilepsy (1); glioblastoma (1); granulomatosis with polyangiitis (1); kidney cancer (1); lymph node metastases (1); McLeod syndrome (1); neurological disorders (1); Parkinson disease (1); Pelizaeus-Merzbacher disease (1); peripheral arterial disease (1); retinitis pigmentosa (1); T-cell acute lymphoblastic leukemia (1); T-cell leukemia (1); tooth agenesis (1); type 2 diabetes (1); uterine leiomyosarcoma (1); Wolf-Hirschhorn syndrome (1); X-linked disease (1).